NLRP3 (NLR family pyrin domain containing 3)
Diseases named in the same sentence as NLRP3 in open-access papers (continued):
Sharing a sentence is not in itself a finding about the gene and the disease.
cardiomyopathy (continued). "The recombinant form of the anti-fibrotic hormone, relaxin (RLX), suppresses the pro-fibrotic influence of TGF-β1 and toll-like receptor (TLR)-4 on NLRP3 inflammasome priming and activity in human cardiac myofibroblasts and mice with cardiomyopathy." (PMID 32848798, 2020). "We subsequently investigated whether changes in NLRP3 expression could serve as a marker for cardiomyopathy and examined its relationship with cardiac function." (PMID 39273638, 2024). "Furthermore, vericiguat reduces chemokines and cytokines involved in cardiomyopathies through NLR family pyrin domain containing 3 (NLRP-3) pathways in human cardiomyocytes and skeletal muscle cells." (PMID 38672567, 2024). "The NLRP3 inflammasome is a crucial cytokine that promotes the development of cardiomyopathy." (PMID 37123477, 2023). "Therefore, ROS plays a central role in the activation of oxidative stress and NLRP3-mediated inflammation, resulting in the occurrence of Ang II-induced cardiomyopathy." (PMID 36978920, 2023). "Recent studies have identified the NLRP3 inflammasome as a key nodal point in the pathogenesis of cardiomyopathies and heart dysfunction, which may create an opportunity to develop new therapeutic agents." (PMID 35739940, 2022). "Endotoxemia-induced mortality and cardiomyopathy are reduced by Sodium tanshinone IIA sulfonate, which may be linked to NLRP3 inflammasome suppression." (PMID 35873572, 2022). "This study was aimed to determine whether Nlrp3 inflammasome activation and its downstream pathway were involved in Ang II-induced cardiomyopathy." (PMID 33628380, 2021). "As a vital mediator of inflammation, the role of the Nlrp3 inflammasome in Ang II-induced cardiomyopathy remains unclear." (PMID 33628380, 2021). "Based on available experimental evidence, targeting the NLRP3 inflammasome-signaling pathway may represent a unique therapeutic opportunity for patients with cardiomyopathy and/or AF." (PMID 30150941, 2018). "However, the effects and potential downstream pathway of Nlrp3 inflammasome activation in Ang II-induced cardiomyopathy remain unclear." (PMID 33628380, 2021). "In the present study, we investigated the effects and potential downstream pathway of Nlrp3 inflammasome activation in Ang II-induced cardiomyopathy, and whether targeting the Nlrp3 inflammasome could be a novel therapeutic approach for the treatment of Ang II-induced cardiac diseases." (PMID 33628380, 2021).
autoinflammatory syndrome (52 papers, 2007 to 2026). A group of disorders of the innate immune system characterized by attacks of seemingly unprovoked inflammation without significant levels of either autoantibodies or autoreactive T cells more characteristic of autoimmune disease. "Aberrant or persistent activation of NLRP3 has been implicated in the pathogenesis of numerous disorders, including autoinflammatory syndromes, metabolic and cardiovascular diseases, neurodegenerative conditions, and cancers." (PMID 41799937, 2026). "The dysregulated activation of Nlrp3 has been implicated in a range of conditions, including autoinflammatory syndromes, metabolic disorders, and neurodegenerative diseases." (PMID 40002829, 2025). "For example, autoinflammatory syndromes with gain-of-function mutations in NLRP3 are mainly driven by myeloid-production of IL-1β, while syndromes due to gain-of-function mutations in NLRC4 are associated with epithelial-production of IL-18." (PMID 39468985, 2024). "The NLRP3 gene mutations associated with autoinflammatory syndromes have been found in some CNO patients, as mentioned, and similar genetic mutations are implicated in IBD." (PMID 38137947, 2023). "Cryopyrin-associated periodic syndrome (CAPS) is an autoinflammatory syndrome caused by mutations of NLRP3 gene encoding cryopyrin." (PMID 35616535, 2022). "In contrast to deficiencies in innate immunity, we also identified an association between eosinophilia and NLRP3-mediated autoinflammatory syndromes." (PMID 35273610, 2022). "The NLRP3 inhibitor MCC950 is able to impair constitutive oligomers of NLRP3 with different mutations associated to autoinflammatory syndromes." (PMID 33803783, 2021). "In conclusion, the evidence we report in our study supports an association between NLRP3 Q703K and the risk of autoinflammatory syndromes, as indicated by the significantly increased prevalence of this variant in our PFAPA, CAPS and uAID populations." (PMID 32477355, 2020). "The relevance of NLRP3 mutations as key players in the induction of these autoinflammatory syndromes has been explored in animal models." (PMID 28191008, 2017). "Roles of type I IFNs have also been shown in familial Mediterranean fever, an autoinflammatory syndrome associated with NLRP3 dysregulation and aberrant IL-1β secretion." (PMID 25486008, 2014). "NLR mutations are associated with auto-inflammatory syndromes, and our previous data propose NLRP3 (Q705K)/CARD-8 (C10X) polymorphisms to contribute to increased risk and severity of inflammatory disease by acting as genetic susceptibility factors." (PMID 22403613, 2012). "In many aspects, the Schnitzler syndrome resembles the genetically determined auto-inflammatory syndromes involving activating mutations of the NLRP3 inflammasome." (PMID 21143856, 2010). "Therefore, genetic mutations in the NLRP3 inflammasome are key drivers of autoinflammatory syndromes." (PMID 40307577, 2025). "However, the abnormal activation of the NLRP3 inflammasome due to mutations in the NLRP3 gene in humans has been linked to specific autoinflammatory syndromes and metabolic issues." (PMID 38891697, 2024). "There has been a plethora of studies associating various gain-of-function mutations in NLRP3 with several autoinflammatory syndromes, and this has been supported by mechanistic studies illustrating a direct causal relationship between specific NLRP3 mutations and inflammatory sequelae." (PMID 34638239, 2021). "Recent research has led to novel findings in inflammasome biology and genetics that altered the diagnosis and management of patients with autoinflammatory syndromes caused by NLRP3-, Pyrin-, NLRP1-, and NLRC4-inflammasomes and spurred the development of novel treatments." (PMID 32983099, 2020). "Mutated NLRP3 causes autoinflammatory syndromes resulting in excess IL-1β production." (PMID 31319552, 2019).
autoinflammatory syndrome (continued). "In addition to its key antimicrobial role, the inflammasome has been implicated in numerous autoinflammatory syndromes associated with either mutations of receptors such as NLRP3 (also known as cryopyrin) or with the chronic presence of danger signals." (PMID 23630667, 2013). "Previous studies have identified the importance of NLRP3 in rare autoinflammatory syndromes, collectively termed CAPS, in which mutations in the NLRP3 gene cause a group of inherited autoinflammatory disorders." (PMID 40307577, 2025). "To date, there are limited data on the role of IL‐38 in IL‐1β or NLRP3 related auto‐inflammatory syndromes." (PMID 33620105, 2021). "NLRP3 inflammasomes are hallmarks of multiple autoinflammatory syndromes and are involved in the pathogenesis of metabolic disorders." (PMID 32560503, 2020). "In a previous study, using a next generation sequencing approach, we found many rare variants and some functional polymorphisms in genes related to autoinflammatory syndromes (AID): CECR1, MEFV, MVK, NLRP3, NOD2, PSTPIP1 and TNFRSF1A in our BD cohort." (PMID 30808881, 2019). "NLRP3 gain‐function mutation has been shown to cause Muckle–Wells syndrome (MWS), which is an autoinflammatory syndrome characterized by an excessive secretion of IL‐1β." (PMID 29531021, 2018). "The most prominent member of NLR family in the study of hereditary autoinflammatory syndromes is NLRP3." (PMID 28191008, 2017). "Further investigation is required to elucidate the role of NEK7 in the auto-activation of NLRP3 inflammasome in autoinflammatory syndromes." (PMID 28191008, 2017). "The overproduction of IL-1β, induced by NLRP3 inflammasome activation, is responsible for a variety of autoinflammatory syndrome including FMF." (PMID 23437051, 2013). "On the other hand, blocking IL-1β by anakinra in patients with the autoinflammatory syndrome neonatal-onset multisystem inflammatory disease (NOMID), a disease caused by autosomal dominant mutations in CIAS1 or NLRP3, reduces systemic and organ-specific inflammation but not the bone manifestations." (PMID 25954061, 2015). "IL-1β, IL-18, and IL-33 were within normal limits or undetectable, and no mutations were found in genes related to the pathogenesis of autoinflammatory syndromes (MEFV, MVK, TNFRSF1A, NLRP3, and NLRP12)." (PMID 34829952, 2021). "Although the NLRP3 inhibitor CRID3 (also known as MCC950) exhibits potent activity, it cannot inhibit several hyperactive NLRP3 mutations associated with autoinflammatory syndromes and has not progressed clinically, underscoring the need for the development of new NLRP3 inhibitors." (PMID 41998138, 2026).
glioma (49 papers, 2016 to 2025). A benign or malignant brain and spinal cord tumor that arises from glial cells (astrocytes, oligodendrocytes, ependymal cells). "The activation of the NLRP3 inflammasome is associated with glioma cell proliferation, migration, and metastasis." (PMID 37107298, 2023). "Both NLRC4 and NLRP3 have been found to be upregulated and associated with poor prognosis in glioma." (PMID 38002346, 2023). "S100A8/S100A9 are also implicated in the activation of the NLRP3 inflammasome, which has been shown to play a role in glioma progression." (PMID 34975408, 2021). "Collectively, these data indicate that both NLRC4 and NLRP3 are upregulated in gliomas and suggest that they potentially associated with glioma progression." (PMID 31133717, 2019). "Finally, the results of GSEA indicated that CASP4 is involved in the glioma-associated NLRP3-inflammation complex as well as immune signaling pathways such as T cell activation and proliferation and chemokine activation." (PMID 39075190, 2024). "Basic research identifies NLRP3 inflammasomes as crucial molecular connectors between brain aging and glioma progression, with NLRP3 proposed as a predictive glioma biomarker." (PMID 41208649, 2025). "Preclinical studies involving STING agonists, TLR modulators, and NLRP3 inhibitors are being studied in regard to how they alter the TME in gliomas." (PMID 41157253, 2025). "NLRP3 activation in gliomas occurs in microglia and infiltrating macrophages but it can also be stimulated in tumor cells themselves." (PMID 41157253, 2025). "In C6 glioma cells, inhibition of NLRP3 through beta-hydroxybutyrate (BHB) reduces caspase-1 and suppresses cell migration, likely by reducing ACS oligomerization or preventing K+ efflux." (PMID 41291696, 2025). "NLRP3 inhibition suppresses senescence‐related gene expression, thereby attenuating glioma proliferation." (PMID 41208649, 2025). "Accumulating recent evidence suggests that NLRP3 contributes to glioma progression by enabling an immunosuppressive microenvironment and facilitating invasion." (PMID 41463173, 2025). "XHP promotes cellular pyroptosis by regulating the POU4F1/STAT3/NLRP3 pathway and inhibits glioma malignant progression." (PMID 38957318, 2024). "Simultaneously, we demonstrated that inhibiting p-STAT3 through EZH2 enhances NLRP3 inflammasome activity, promoting glioma pyroptosis and the expression of inflammatory factors IL-1β and IL-18." (PMID 39069522, 2024). "In further studies, calycosin inhibits glioblastoma cell proliferation and invasivion, migratory properties by decreasing downstream inflammatory cytokines, including NLRP3, NF‐B, and IL‐1 in glioma cell lines U251, U87, and BALB/c mice." (PMID 38230908, 2024). "WP1066, which inhibits the activation of STAT3 by directly targeting JAKs, also suppresses glioma cells via NLRP3 inflammasome inhibition independently of STAT3 inhibition." (PMID 37723542, 2023). "Considering these findings, the outline of the potential axis of the NLRP3 inflammasome involved in the induction and regulation of gliomas has been revealed." (PMID 37723542, 2023). "Aggressive expression and activity of the NLRP3 inflammasome were observed in cells derived from glioma patients, suggesting that the NLRP3 inflammasome is a potential marker of glioma progression." (PMID 37723542, 2023). "Activation of NLRP3 triggers the downregulation of miRNA-214, which inhibits glioma cell proliferation and migration by targeting caspase-1." (PMID 38002346, 2023). "Ever since the pathological function of NLRP3 in glioma was understood, its regulatory mechanisms and potential as a therapeutic target have been evaluated." (PMID 37723542, 2023). "Beta-hydroxybutyrate (BHB) inhibits the migration of glioma by suppressing NLRP3 inflammasome expression and activation." (PMID 37723542, 2023). "Another report has exhibited that the NLRP3 inflammasome induces proliferation and invasion of glioma cells via regulation of IL-1β and NF-κB p65 signaling." (PMID 37723542, 2023).
glioma (continued). "The activation of NLRP3 can trigger the downregulation of miRNA-214, which inhibits glioma cell proliferation and migration." (PMID 38002346, 2023). "BHB, WP1066, and IP-Se-06 were found to directly inhibit glioma migration, proliferation, and viability by inhibiting the expression or activity of the NLRP3 inflammasome in glioma." (PMID 37723542, 2023). "Fewer reports of NLRP6 in glioma have been made compared to NLRP3 and NLRC4, but some progress has been made in recent years." (PMID 37723542, 2023). "We also examined the effects of Tim-3/Gal-9 on the NLRP3 inflammasome in glioma cells and showed that the NLRP3 inflammasome was regulated by Tim-3/Gal-9 similarly to the NLRC4 inflammasome." (PMID 35216164, 2022). "Blocking NF-κB attenuates IL-1β and NLRP3 overexpression and increases cell growth and invasion, and NLRP3 promotes glioma growth and invasion through IL-1β/ NF-κB P65 signaling." (PMID 36401196, 2022). "The role of the NLRP3 inflammasome and its components has also been extensively described in gliomas, a group of malignant neoplasms of the central nervous system, which led to the identification of a protumoral role for NLRP3." (PMID 34064909, 2021). "It was reported that the inhibition of the NLRP3 inflammasome by beta-hydroxybutyrate can suppress the migration of glioma cells." (PMID 35069683, 2021). "The upregulation of NLRP3 affects human glioma progression by activating the AKT signaling pathway and IL-1β/NF-kappaB p65 signaling, thus promoting migration and invasion." (PMID 34064909, 2021). "In contrast, NLRP3 overexpression promotes the growth and invasion of gliomas through IL-1β/NF-κB p65 signaling." (PMID 34239588, 2021). "Overexpression of NLRP3 promotes cell proliferation and colony formation in glioma cells, whereas the downregulation of NLRP3 significantly repressed colony formation in glioma cells." (PMID 33613533, 2020). "As expected, β-hydroxybutyrate inhibited the migration of C6 glioma cells by suppressing the activation of the NLRP3 inflammasome." (PMID 31492049, 2019). "To investigate NLRC4 and NLRP3 inflammasomes as potential prognostic markers in glioma patients, we compared NLRP3 or NLRC4 expression with survival using TCGA data." (PMID 31133717, 2019). "As there is a report demonstrating that human malignant gliomas activate NLRP3 inflammasomes and express IL-1β17, we sought to further investigate the connection between inflammasomes and gliomas." (PMID 31133717, 2019). "Mechanistically, NLRP3 regulated glioma progression and metastasis via its effects on the EMT program and the phosphatase and tensin homolog (PTEN)/protein kinase B (Akt) signaling pathway." (PMID 31492049, 2019). "NLRP3 promoted the proliferation, invasion and migration, as well as suppressed the apoptosis of glioma cells." (PMID 31492049, 2019). "In conclusion, the histological and bioinformatics analyses of tissue samples and TCGA data from glioma patients provide evidence that NLRC4 and NLRP3 inflammasomes are activated in gliomas." (PMID 31133717, 2019). "Whereas both NLRP3 and NLRC4 were expressed in the brain and colocalized with caspase-1, only NLRC4’s expression was elevated in glioma samples and correlated with poor diagnostic of these patients." (PMID 31892810, 2019). "Our results along with previous studies suggest that IL-1β, after being secreted by activated microglia, induces its own production by stimulating NLRP3 inflammasome complex in glioma cells, monocytes, and other cell types." (PMID 29885667, 2018). "They demonstrated that NLRP3 inflammasome was a molecular link between brain aging and progression of glioma and radiotherapy resistance." (PMID 27652274, 2016). "Additionally, the NLRP3 inflammasome can regulate the NF-κB p65 and IL-1β signaling to induce glioma cell invasion and proliferation." (PMID 41157253, 2025).